STAT3 (signal transducer and activator of transcription 3)
Diseases named in the same sentence as STAT3 in open-access papers (continued):
Sharing a sentence is not in itself a finding about the gene and the disease.
ovarian carcinoma (continued). "Interestingly, a recent study suggests that STAT3 is positively associated with expression of MMP9 in epithelial ovarian cancer." (PMID 31949487, 2020). "Persistent STAT3 activation in colon cancer is associated with enhanced cell proliferation and tumor growth, and tumor derived exosomes have been shown to activate the phosphorylation of STAT3 in ovarian cancer cells." (PMID 31402975, 2019). "Our findings showed that blockade of AKT or STAT3 may benefit ovarian cancer patients harboring PIK3R1 copy number loss or reduced PIK3R1 expression." (PMID 30755611, 2019). "PIK3R1 loss renders ovarian cancer cells vulnerable to inhibition of AKT or JAK2/STAT3." (PMID 30755611, 2019). "Recently, it was found that activated STAT3 may deploy specific microRNAs to promote ovarian cancer cell proliferation and to generate associated phenotypes." (PMID 31861720, 2019). "The finding that miR551b and high glutamate levels were associated with activation of STAT3 in invasive ovarian cancer further support the hypothesis that STAT3 has a role in cellular metabolism." (PMID 31130718, 2019). "However, the underlying mechanism of STAT3 in association with autophagy and chemoresistance in ovarian cancer is quite ambiguous." (PMID 31597912, 2019). "Both STAT3 and PD-L1 expression are associated with chemoresistance in ovarian cancers." (PMID 30127274, 2018). "However, in cancer cells STAT3 is constitutively activated, and its persistent activation is associated with a poor prognosis in cancer patients, including ovarian cancer patients." (PMID 29849942, 2018). "Constitutive activation of STAT3 is causally linked to tumor development and progression in various types of solid malignancies, including head and neck cancer, myeloma, prostate cancer, breast cancer, colon cancer, and ovarian cancer." (PMID 29050266, 2017). "Here, we show epithelial ovarian cancer (EOC)-derived exosomes activated macrophages to a tumor-associated macrophage (TAM)-like phenotype with SOCS3/STAT3 pathway involvement, which could facilitate the progression of cancer." (PMID 27172798, 2016). "Persistent activation of STAT3 plays a critical role in tumor progression by promoting cell proliferation, cell survival, angiogenesis and tumor immune evasion, and is associated with a poor prognosis for ovarian cancer patients." (PMID 25928246, 2015). "However, in ovarian cancer it is known that tyrosine phosphorylation is mainly associated with oncogenic status of STAT3." (PMID 23593315, 2013). "We studied the association between the increased levels of STAT3 activation and high-grade ovarian carcinomas, consistent with a role for STAT3 in the motile phenotype of ovarian cancer cells in response to direct activation by EGFR or indirectly through IL-6R." (PMID 19088723, 2009). "Therefore, our findings indicate that PARPi treatment-associated p-STAT3 upregulation in ovarian cancer patient tumor-associated immune cells and CAFs may contribute to disease progression by promoting therapy resistance and immunosuppression." (PMID 34956861, 2021). "Importantly, STAT3 blockade led to Olaparib-resistant cell growth inhibition, and lower Napabucasin concentrations re-sensitized resistant BRCA-wildtype and BRCA2-mutated ovarian cancer cells to Olaparib in vitro, further supporting the notion that STAT3 activity promotes PARPi resistance." (PMID 34956861, 2021). "In the current study, we investigated whether PARPi treatments in ovarian cancer patients induce STAT3 activation in tumor cells and the tumor immuno-microenvironment and whether PARPi-mediated STAT3 activation underlies PARPi resistance and immunosuppression in ovarian cancer." (PMID 34956861, 2021). "However, whether STAT3/p-STAT3 expression is associated with clinicopathologic characteristics and has prognostic significance for people suffering from ovarian cancer remains controversial." (PMID 34789292, 2021).
ovarian carcinoma (continued). "STAT3 signaling has long been known to play a critical role in immune tolerance and inhibition of tumor immune surveillance, and multiple studies point to a central role for STAT3 signaling as a key driver of immune suppression by tumor-associated macrophages and M2 polarization in ovarian cancer." (PMID 26343197, 2015). "Hence, targeting EpCAM+++ ovarian tumor cells and/or the associated STAT3 pathway in combination with chemotherapy may help achieve durable clinical responses in recurrent ovarian cancer patients." (PMID 23056490, 2012). "Furthermore, STAT3 is also implicated in resistance to chemotherapy in ovarian cancer." (PMID 22280969, 2012). "In this study, we show that EGF regulates many of the key processes that lead to mesenchymal transition in epithelial ovarian cancer cells and that autocrine signalling through the IL6-R/JAK2/STAT3 pathway is associated with these events and may regulate the metastasis of ovarian carcinoma." (PMID 19088723, 2009). "As a vital immunoregulatory cytokine, IL‐6 mediates chemoresistance through various signaling pathways, with the JAK2/STAT3 signaling pathway being particularly prominent in ovarian cancer." (PMID 40968783, 2026). "Accumulating evidence has shown that phosphorylated STAT3 is highly expressed in Paclitaxel‐resistant and cisplatin‐resistant ovarian cancer cell lines." (PMID 40968783, 2026). "This IL-8/STAT3 axis plays a crucial role in promoting the M2 polarization, fostering a tumor-friendly environment that supports cancer progression and stemness in ovarian cancer cells." (PMID 40330466, 2025). "Given the very promising and specific SKOV3 viability reduction that we observed for anti-STAT3 mcDNA in the MTS assay, we proceeded to evaluate the underlying effects of our compound on apoptosis and necrosis in these representative ovarian cancer cells." (PMID 41031165, 2025). "MCP inhibits STAT3 phosphorylation and galectin-3, suppressing M2 macrophages and STAT3 signaling in breast, prostate, and ovarian cancers." (PMID 41346617, 2025). "The co-culture of ovarian cancer stem-like cells (OCSLCs) with macrophages derived from THP-1 cells promoted stemness in SKOV3 ovarian cancer cells through the IL-8/STAT3 signaling pathway." (PMID 40330466, 2025). "IL-6 additionally induces nuclear translocation and transcriptional activation of HIF-1α via STAT3, enhancing cisplatin resistance in ovarian cancer cells." (PMID 41383608, 2025). "Regarding OC, CAAs induce the activation of the signal transducer and activator of transcription 3 (STAT3) signaling pathway in ovarian cancer cells and thereby initiate autophagy and trigger the expression of genes involved in cell proliferation." (PMID 40076482, 2025). "Immunohistochemistry for JAK1, STAT1, and STAT3 was performed on samples of patients with ovarian cancer to confirm the correlation between JAK-STAT family expression and platinum treatment response." (PMID 40883550, 2025). "Quercetin has induced autophagy and apoptosis through ER (endoplasmic reticulum) stress via the p‐STAT3/Bcl‐2 axis in ovarian cancer SKOV‐3 cells." (PMID 40634118, 2025). "Studies have indicated that curcumin amplifies the anti-inflammatory properties of Tehranolide via modulating the STAT3/NF-κB signaling cascade in ovarian cancer cell lines." (PMID 41009742, 2025). "Recent evidence indicates that IL-6 and STAT3 are pivotal in the advancement of ovarian cancer, potentially through the polarization of TAMs." (PMID 40443670, 2025). "In ovarian cancer cell lines (SKOV3, RMG-1, and ES-2), CA inhibited cell proliferation and increased apoptosis by downregulating STAT3, a key pathway associated with tumor growth, chemoresistance, and immune suppression." (PMID 40330466, 2025). "The activation of the APJ receptor induces the STAT3 pathway, leading to increased CD36 expression, which causes increased lipid transport and lipid droplet accumulation in ovarian cancer cells." (PMID 40076482, 2025).
ovarian carcinoma (continued). "Suppresses ovarian cancer cell proliferation and macrophage-induced protumor effects by inhibiting STAT3; reduces IL-10 and other M2 markers in macrophages; enhances sensitivity to chemotherapy drugs (e.g., CDDP, PTX) in cancer cells." (PMID 40330466, 2025). "Enhances chemosensitivity in ovarian cancer cells by inhibiting STAT3 signaling; reduces tumor-promoting macrophage interactions with cancer cells; synergistic with chemotherapy agents like paclitaxel and cisplatin." (PMID 40330466, 2025). "Our findings support further development toward preclinical validation and, ultimately, clinical application of this technology, not only in ovarian cancer but also in other STAT3-driven malignancies." (PMID 41031165, 2025). "This work provides an initial proof-of-concept for a novel circular DNA-based inhibitor that effectively impairs cell growth and survival in vitro in the SKOV3 model for ovarian cancer via specific modulation of STAT3 activity." (PMID 41031165, 2025). "In female reproduction, miR-551b-3p binds to the STAT3 promoter complementary sequence, recruits RNA polymerase II and TWIST1 transcription factors, activates STAT3 transcription, and upregulates STAT3 expression in ovarian cancer cells." (PMID 39940713, 2025). "The SKOV3 ovarian cancer cell line, characterized by the fifth highest level of STAT3 expression, was chosen as our model." (PMID 41031165, 2025). "For instance, ovarian cancer-derived EVs carrying miR-21-3p have been found to enter resident macrophages at distant sites and activate the STAT3 signaling pathway, driving these macrophages into an immunosuppressive M2 state." (PMID 40574836, 2025). "This miRNA’s role in regulating the CASR/STAT3 axis indicates its potential as a therapeutic target to counteract chemoresistance in ovarian cancer." (PMID 40757000, 2025). "For instance, one study demonstrated that LCP1 contributes to olaparib resistance by activating the JAK2/STAT3 signaling pathway in ovarian cancer." (PMID 40740857, 2025). "The JAK1/STAT3 pathway has been studied extensively in ovarian cancer in multiple models, identifying this pathway as a potential target." (PMID 40806640, 2025). "In ovarian cancer, EVs carrying miR-21-3p reach the pre-metastatic niche, activating the STAT3 pathway and promoting M2 macrophage polarization." (PMID 40574836, 2025). "In breast and ovarian cancer models, curcumin’s direct inhibition of STAT3 phosphorylation prevents its nuclear translocation and DNA binding, thereby suppressing transcription of genes related to cell survival, proliferation, metastasis, and chemoresistance." (PMID 41020838, 2025). "This is the main strategy we envision for a future safe personalized ovarian cancer therapy utilizing the anti-STAT3 mcDNA developed in this study." (PMID 41031165, 2025). "From a diagnostic perspective, molecular profiling techniques can be employed to assess the activation status of the STAT3 pathway in ovarian cancer patients." (PMID 40836974, 2024). "Studies indicate that STAT3 contributes to the invasiveness of ovarian cancer by regulating cell motility through nuclei localization as well as focal adhesion, suggesting it is a potential target for therapeutic intervention." (PMID 39766086, 2024). "In ovarian cancer, the activation of STAT3 has been shown to induce anoikis resistance by altering extracellular matrix production, thus promoting cancer progression." (PMID 38226979, 2024). "We reported that abnormal expression of LCP1 led to ovarian cancer cell resistance to olaparib by activating the JAK2/STAT3 signaling pathway and EMT." (PMID 39588922, 2024). "Specifically, JAK2 upregulation and JAK2/STAT3 pathway activation have critical roles in several solid tumors and significantly influence the survival of patients with ovarian cancers." (PMID 38256218, 2024).
ovarian carcinoma (continued). "Specifically, chronic stress elevates stress hormone levels, stimulates relative receptors, and subsequently decreases HDC expression, promoting ovarian cancer progression via the IL-6/STAT3/S100A9 pathway." (PMID 39720595, 2024). "Overall, these results indicated that HDC downregulation induced by stress hormones promoted the proliferation, migration, and invasion of ovarian cancer cells through activation of the IL-6/STAT3/S100A9 signaling pathway." (PMID 39720595, 2024). "The deterioration of the G2 arrest under the hypoxic environment of 1% O2 has also been validated in SKOV3 human ovarian cancer cells following treatment with Paclitaxel, postulating the inhibition of the Src/Stat3/HIF-1α pathway as a potential mechanism." (PMID 39684302, 2024). "Other studies demonstrated that high concentrations of QCT induced endoplasmic reticulum stress via the p‐STAT3/Bcl‐2 axis in ovarian cancer cells, inducing apoptosis." (PMID 39162596, 2024). "Subsequently, STAT3 activation resulted into the upregulation of integrins which in turn contributed into the STAT3 activation for a prolonged period as a critical mechanism in highly aggressive ovarian cancer cells like cisplatin-resistant cells." (PMID 38839865, 2024). "Preclinical studies show that activation of the JAK-STAT3 pathway in triple negative breast cancer (TNBC) or the FGFR1/SRC/STAT3 pathway in ovarian cancer promotes tumor initiation, migration, and paclitaxel resistance." (PMID 39200368, 2024). "In summary, in this study, we demonstrated that LCP1 is involved in olaparib resistance in ovarian cancer cells by activating the JAK2/STAT3 pathway and EMT." (PMID 39588922, 2024). "From a therapeutic perspective, the novel small molecule LLL12B has emerged as a potent inhibitor of the STAT3 pathway in human ovarian cancer cells." (PMID 40836974, 2024). "In our previous work, we have shown that STAT3, a major oncoprotein in ovarian cancer, is highly activated in the ascites." (PMID 38939897, 2024). "For instance, ovarian cancer cell-derived exosomes carrying the PKR1 protein have been shown to activate the PKR1 signaling pathway by inducing STAT3 phosphorylation in human umbilical vein endothelial cells (HUVECs)." (PMID 39334866, 2024). "We demonstrated that LCP1 can promote EMT by activating the JAK2/STAT3 signaling pathway in ovarian cancer cells, thereby promoting tumor cell metastasis and invasion." (PMID 39588922, 2024). "Hypoxic ovarian cancer cell exosomes carrying STAT3 and FAS significantly increase chemotherapy resistance in vitro." (PMID 39334866, 2024). "The LCP1/JAK2/STAT3 axis is a key signaling pathway involved in olaparib resistance in ovarian cancer." (PMID 39588922, 2024). "We also tested STAT3 activation as STAT3 has also been shown to be activated in cisplatin resistant ovarian cancer cells." (PMID 38745302, 2024). "PBX1 further upregulates the signal transducer and activator of transcription 3 (STAT3) expression through transcription, thereby enhancing the resistance of ovarian cancer cells to carboplatin." (PMID 39090090, 2024). "Separate investigations of EGFR inhibition in NSCLC and ovarian cancer models identified activation of STAT3 as being critical to the drug-tolerant state." (PMID 38473364, 2024). "The PTP4A phosphatase inhibitor, JMS-053 treatment reduces Y705 phospho-STAT3 in ovarian cancer cells." (PMID 40836974, 2024). "Chronic stress leads to the downregulation of HDC expression, thereby facilitating the progression of ovarian cancer through the IL-6/STAT3/S100A9 pathway." (PMID 39720595, 2024). "For example, recent work has shown that the release of lactate from TNBC cells or chemokine ligand 2 (CCL2) from ovarian cancer cells induces the chemotaxis of macrophages, STAT3 signaling, and M2 differentiation." (PMID 39200368, 2024).
ovarian carcinoma (continued). "In ovarian cancer cells, MTHFD2 promoted cancer cell progression by activating the signal transducer and activator of transcription 3 (STAT3) pathway, which has been implicated in cancer cell proliferation and metastasis." (PMID 40604332, 2024). "In a mouse model of human ovarian carcinoma, STAT3 regulated formation of spheroids and self-renewal, while attenuation of STAT3 decreased the tumorigenicity." (PMID 39513610, 2024). "In ovarian cancer, LINC00852 acts as the ceRNA of miR-140-3p to promote AGTR1 expression and activate the MEK/ERK/STAT3 pathway, thereby promoting the proliferation and invasion of ovarian cancer cells." (PMID 36983741, 2023). "The SLN-STAT3 ODN-decoy induced ovarian cancer cell apoptosis, which was higher than the apoptosis of cancer cells after naked STAT3 ODN-decoy application." (PMID 38067351, 2023). "It has shown anti-IL-6 activity, which induces inactivation of STAT3 through IL-6 binding and nuclear accumulation of FoxO3a in ovarian cancer cells." (PMID 37047012, 2023). "According to a number of studies, total STAT3 and phosphorylated STAT3 (p-STAT3) are overexpressed in a subgroup of chemotherapy-resistant ovarian cancer cell lines compared to their expression in the corresponding chemotherapy-sensitive cell lines." (PMID 36768291, 2023). "An excellent cellular uptake of siRNA-loaded particles and effective STAT3 silencing in SKOV3 ovarian cancer cells were observed." (PMID 38067351, 2023). "STAT3 regulates Rab7 and Rab27a under hypoxic conditions and increases exosome release in ovarian cancer cells by promoting a more secretory lysosomal phenotype." (PMID 37497408, 2023). "These molecular docking findings indicated strong interactions between pachyman with SRC and STAT3 and the potential pharmacological targets against ovarian cancer." (PMID 37831733, 2023). "Another study discovered that overexpression of STAT3 induced M2 macrophage polarization and stemness in ovarian cancer cells." (PMID 36949762, 2023). "Specifically, STAT3 was shown to be constitutively activated in ovarian cancer cells, and its continued activation is likely predictive of an unfavorable prognosis in patients." (PMID 37190289, 2023). "A recent retrospective study found that the over-expression of STAT3 was seen in the chemo-naïve ovarian tissue of patients with advanced ovarian cancer (19/25, 76.0%) and in both platinum-sensitive (78.6%) and platinum-resistant (72.7%) groups." (PMID 36768291, 2023). "It has been demonstrated that CT inhibited glycolysis via the STAT3/SIRT3 signaling pathway in ovarian cancer cells." (PMID 37375808, 2023). "Further, in vivo study using a tumor model made of CAOV3 ovarian cancer cells with silenced STAT3 indicated that the formed tumor was significantly smaller than the control cells." (PMID 38067351, 2023). "The effect of the STAT3 ODN-decoy on the inhibition of ovarian cancer growth and the induction of cell apoptosis has also been confirmed in in vivo studies." (PMID 38067351, 2023). "Because of the activation of STAT3 by Il-6, it seems that the blockade of Il-6 and inhibition of this marker prolong survival of patients with ovarian cancer." (PMID 37373969, 2023). "This meta-analysis concluded that STAT3/p-STAT3 over-expression likely indicates a poor prognosis in ovarian cancer patients." (PMID 36768291, 2023). "In conclusion, our work reveals an important role of A2B in mediating Olaparib resistance in ovarian cancer cells by activating IL‐6‐STAT3 signalling pathway, highlighting a novel application of A2B and STAT3 inhibition in defeating Olaparib resistance." (PMID 37278400, 2023). "The transfection of CAOV3 ovarian cancer cells with STAT3 shRNA plasmid resulted in a reduction in STAT3 and phosphorylated STAT3 protein amount." (PMID 38067351, 2023). "Mechanistically, low expression of YTHDC1 promotes ovarian cancer tumorigenesis via PIK3R1/STAT3/GANAB axis." (PMID 37781028, 2023).